KCNIP2 (potassium voltage-gated channel interacting protein 2)
Description:
Regulatory subunit of Kv4/D (Shal)-type voltage-gated rapidly inactivating A-type potassium channels. Modulates channel density, inactivation kinetics and rate of recovery from inactivation in a calcium-dependent and isoform-specific manner. Involved in KCND2 and KCND3 trafficking to the cell surface. May be required for the expression of I(To) currents in the heart (By similarity).
Synonyms: KChIP2
Tractability: Antibody: its Gene Ontology location is reachable by antibodies, with high confidence; UniProt places it where antibodies can reach, with medium confidence.
Target class: Transmembrane 1-electron transfer carriers; Transporter
Gene: Protein-coding gene on chromosome 10 (101,825,969 to 101,843,965, reverse strand). Ensembl gene ENSG00000120049.
Subcellular location: Cell membrane (Isoform 1); Cell membrane (Isoform 2); Cell membrane (Isoform 6)
Subcellular location (Human Protein Atlas): Vesicles
Pathways (Reactome):
Muscle contraction: Phase 1 - inactivation of fast Na+ channels
Gene Ontology:
Molecular function: A-type (transient outward) potassium channel activity; potassium channel regulator activity; protein binding; transmembrane transporter binding; calcium ion binding; ER retention sequence binding; protein-containing complex binding
Biological process: action potential; clustering of voltage-gated potassium channels; membrane repolarization; muscle contraction; positive regulation of potassium ion export across plasma membrane; regulation of membrane repolarization; regulation of potassium ion export across plasma membrane; regulation of potassium ion transmembrane transport; chemical synaptic transmission; detection of calcium ion; membrane repolarization during cardiac muscle cell action potential; potassium ion transport; regulation of heart contraction; regulation of signal transduction; signal transduction; potassium ion transmembrane transport
Cellular component: cytoplasm; Kv4.2-KChIP2 channel complex; voltage-gated potassium channel complex; plasma membrane; dendrite; synapse
Genetic constraint (gnomAD): Loss-of-function variants: 18 observed, 34.5 expected, observed/expected ratio (o/e) 0.52, 90% interval 0.36 to 0.77. The upper end of that interval is the gene's LOEUF score, 0.77, which puts it in group 3 of 6, group 1 being the genes least tolerant of losing a copy. Missense variants: 254 observed, 333.65 expected, observed/expected ratio (o/e) 0.76, 90% interval 0.69 to 0.85. Synonymous variants: 109 observed, 124.24 expected, observed/expected ratio (o/e) 0.88, 90% interval 0.75 to 1.03.
Homologues: Orthologues: chimpanzee KCNIP2 (99% identical), pig KCNIP2 (99% identical), guinea pig KCNIP2 (97% identical), rat Kcnip2 (97% identical), rabbit KCNIP2 (94% identical), dog KCNIP2 (93% identical), tropical clawed frog kcnip2 (84% identical), macaque KCNIP2 (77% identical), mouse Kcnip2 (74% identical), zebrafish kcnip2 (52% identical), Drosophila melanogaster CG5890 (36% identical), Caenorhabditis elegans ncs-7 (29% identical), and 2 more. Paralogues in human: KCNIP4 (62% identical), KCNIP3 (59% identical), KCNIP1 (53% identical), NCS1 (32% identical), HPCA (31% identical), HPCAL4 (30% identical), NCALD (30% identical), VSNL1 (30% identical), HPCAL1 (30% identical), RCVRN (24% identical), GUCA1B (23% identical), GUCA1A (21% identical), and 2 more.
Diseases named in the same sentence as KCNIP2 in open-access papers:
KCNIP2 is named in the same sentence as 33 diseases in open-access papers, as found by Europe PMC text mining. Sharing a sentence is not in itself a finding about the gene and the disease. The quoted sentences say what the papers report.
heart failure (16 papers, 2013 to 2023). Inability of the heart to pump blood at an adequate rate to meet tissue metabolic requirements. "Cardiac injuries and subsequent progression to heart failure reactivates Notch signaling in mouse models of heart failure, with concomitant downregulation of Kcnip2, and loss of H3K4me3 associated with dynamic RBP-J binding to the Kcnip2 promoter." (PMID 31346662, 2019). "Given the importance of KCNIP2 in regulating transcription and electrical remodeling in heart failure, understanding how it is regulated will be of clinical importance." (PMID 31346662, 2019). "Additionally, KCNIP2 (an accessory protein that modulates several cardiac ion channels and is involved in cardiac arrhythmia and heart failure) was downregulated by overexpression of a miR-133a genomic precursor in mouse heart." (PMID 23799049, 2013).
Arrhythmia (10 papers, 2013 to 2023). Any cardiac rhythm other than the normal sinus rhythm. "Kcnip2 is a voltage-gated potassium channel cofactor known to alter electrical properties of the heart and altered expression levels can increase susceptibility to arrhythmias." (PMID 26807590, 2016).
glioma (4 papers, 2021 to 2026). A benign or malignant brain and spinal cord tumor that arises from glial cells (astrocytes, oligodendrocytes, ependymal cells). "Among them, high-risk genes MYBL2, C21orf62 and TUBA1C showed higher expression levels in tissues from high-grade gliomas patients (WHO IV grade, GBM), while the expression of low-risk gene KCNIP2 was relatively lower in GBM, which is consistent with our previous hypothesis." (PMID 38577605, 2024). "KCNIP2 gene expression was elevated in grade II and III gliomas compared to grade IV gliomas, and its high expression was significantly associated with prolonged OS." (PMID 40867242, 2025). "A series of genes such as EN1, S100A4, ANXA1, PDPN, IGFBP2 and CHI3L1 were upregulated in radiotherapy treated glioma patients, while other genes such as PRLHR, SFRP2, BRINP1, TRIM67, LHX5, KCNIP2 and NSG2 were downregulated." (PMID 34852024, 2021). "Four PANoptosis-related predictors (MYBL2, TUBA1C, C21orf62 and KCNIP2) were identified and predictive PANRG score model was developed for glioma based on bulk-seq and scRNA-seq analysis, which is significantly associated with tumor immune landscape and therapeutic responses." (PMID 38577605, 2024).
astrocytoma (2 papers, 2025 to 2026). "Analysis of the SHAP values for the remaining genes revealed that increased expression of ZDHHC18, HDAC1, and TUBB6 enhances the probability of predicting astrocytoma, while elevated expression of TERT, TRIM67, NOG, KCNIP2, and KCNJ11 increases the probability of predicting oligodendroglioma." (PMID 40867242, 2025).
Ataxia (1 paper, 2020). Ataxia refers to impaired coordination of voluntary muscle movement. "Other genes are related to cytoskeleton remodeling, including Cdh4, Pcdh9, Dock5, Dock3 for the proprioceptors (mutation of Dock3 is known to results in ataxia) and Stom and Pdlim1 for mechanoreceptors, as well as ion channels (Asic1 and Kcnip2 for proprioceptive fate)." (PMID 32826903, 2020).
conduction disorders (1 paper, 2021). "Similar to our differential gene expression analysis, we focused on alternative splicing events affecting genes involved in regulation of cardiac ion transport and previously implicated in conduction disorders — Scn5a, Kcnd3, Kcnip2, Ryr2, and Camk2d." (PMID 33497365, 2021).
Hyperglycemia (1 paper, 2021). An increased concentration of glucose in the blood. "In addition, a study involving a rat model showed that maternal hyperglycemia can alter fetal cardiac function by down-regulating the expression of KCNIP2, the key regulatory factor mediating fetal cardiac electrophysiology and contractile function." (PMID 34193164, 2021).
ovarian carcinoma (1 paper, 2021). A malignant neoplasm originating from the surface ovarian epithelium. "Causal network analysis revealed novel pathways suggesting predicted inhibition of ovarian cancer through master regulator ASCL1 and dataset genes DCX, SEMA6B, HEY2, and KCNIP2." (PMID 35052372, 2021).
ovarian serous cystadenocarcinoma (1 paper, 2019). A malignant serous cystic epithelial neoplasm arising from the ovary. "Recently using genome-wide methylation data analysis, five-methylation signature (SLC39A14, PREX2, KCNIP2, CORO6, and EFNB1) were reported as novel independent prognostic biomarker for patients with ovarian serous cystadenocarcinoma, which significantly associated with OS of patients." (PMID 31608277, 2019).
tumor (2 papers, 2022 to 2024). "In GBM, KCNIP2 was downregulated in tumor tissues and appears to be significantly linked to the overall survival of patients." (PMID 38577605, 2024).
KCNIP2 also shares sentences with these, for which no sentence is quoted: cardiac hypertrophy (8 papers); cardiac disease (4); atrial fibrillation (3); cardiac arrhythmias (3); myocardial infarction (3); Ventricular arrhythmia (3); Brugada syndrome (2); epilepsy (2); glioblastoma (2); hypertrophy (2); oligodendroglioma (2); ventricular tachycardia (2); aortic coarctation (1); breast carcinoma (1); cardiomyopathies (1); congenital stationary night blindness (1); dilated cardiomyopathy (1); genetic generalized epilepsy (1); malignant (1); myopathy (1); Noonan syndrome (1); Obesity (1); type 2 diabetes (1).